SETSIP (SET like protein)
Description:
Plays a role as a transcriptional activator involved in the early stage of somatic cell reprogramming. Promotes the differentiation of protein-induced pluripotent stem (PiPS) cells into endothelial cells and the formation of vascular-like tubes (in vitro). Involved in the transcription induction of vascular endothelial-cadherin (VE-cadherin) expression. Associates to the VE-cadherin gene promoter.
Synonyms: SETP18
Tractability: PROTAC: ubiquitination databases record sites on it.
Gene: Protein-coding gene on chromosome 1 (92,074,533 to 92,075,411, reverse strand). Ensembl gene ENSG00000230667.
Subcellular location: Cytoplasm; Nucleus
Subcellular location (Human Protein Atlas): Nucleoplasm; Lipid droplets
Gene Ontology:
Molecular function: chromatin binding
Biological process: endothelial cell differentiation; positive regulation of transcription by RNA polymerase II; nucleosome assembly
Cellular component: cytoplasm; lipid droplet; nucleoplasm; nucleus; chromatin
Genetic constraint (gnomAD): Loss-of-function variants: 15 observed, 21.18 expected, observed/expected ratio (o/e) 0.71, 90% interval 0.47 to 1.09. The upper end of that interval is the gene's LOEUF score, 1.09, which puts it in group 4 of 6, group 1 being the genes least tolerant of losing a copy. Missense variants: 310 observed, 338.92 expected, observed/expected ratio (o/e) 0.91, 90% interval 0.83 to 1. Synonymous variants: 101 observed, 121.29 expected, observed/expected ratio (o/e) 0.83, 90% interval 0.71 to 0.98.
Homologues: Orthologues: macaque SETSIP (90% identical), mouse Set (89% identical), rat Setsip (83% identical), chimpanzee SETSIP (81% identical), Drosophila melanogaster Set (49% identical), Caenorhabditis elegans spr-2 (38% identical), zebrafish tspy (34% identical), zebrafish nap1l4a (26% identical), Drosophila melanogaster Nap1 (24% identical), Caenorhabditis elegans nap-1 (20% identical), Drosophila melanogaster CG3708 (18% identical), Drosophila melanogaster mil (18% identical). Paralogues in human: SET (84% identical), TSPYL2 (39% identical), NAP1L1 (33% identical), TSPYL5 (33% identical), TSPYL4 (32% identical), TSPYL1 (32% identical), NAP1L4 (30% identical), TSPYL6 (28% identical), TSPY1 (26% identical), TSPY10 (26% identical), TSPY2 (26% identical), TSPY3 (26% identical), and 6 more.
Diseases named in the same sentence as SETSIP in open-access papers:
SETSIP is named in the same sentence as 1 disease in open-access papers, as found by Europe PMC text mining. Sharing a sentence is not in itself a finding about the gene and the disease. The quoted sentences say what the papers report.
tumor (1 paper, 2019). "The third identified peptide has a specific sequence of AQNADELEEYSASKHDGGSC, which can be realigned to multiple tumor-associated proteins, such as mediator of RNA polymerase II transcription subunit 1, protein FAM45A, and protein SETSIP." (PMID 31850330, 2019).